TAS2R50 (taste 2 receptor member 50)
Description:
Receptor that may play a role in the perception of bitterness and is gustducin-linked. May play a role in sensing the chemical composition of the gastrointestinal content. The activity of this receptor may stimulate alpha gustducin, mediate PLC-beta-2 activation and lead to the gating of TRPM5 (By similarity).
Synonyms: T2R50; T2R51; TAS2R51
Tractability: Antibody: its Gene Ontology location is reachable by antibodies, with high confidence; UniProt predicts a signal peptide or a membrane-spanning region. PROTAC: a small molecule that binds it is known.
Target class: Membrane receptor; Taste receptor (taste family GPCR); Taste family G protein-coupled receptor
Gene: Protein-coding gene on chromosome 12 (10,985,913 to 10,986,912, reverse strand). Ensembl gene ENSG00000212126.
Subcellular location: Membrane
Pathways (Reactome):
Signal Transduction: Class C/3 (Metabotropic glutamate/pheromone receptors); G alpha (i) signalling events
Sensory Perception: Sensory perception of sweet, bitter, and umami (glutamate) taste
Gene Ontology:
Molecular function: bitter taste receptor activity; G protein-coupled receptor activity
Biological process: detection of chemical stimulus involved in sensory perception of bitter taste; G protein-coupled receptor signaling pathway; sensory perception of taste
Cellular component: membrane; plasma membrane
Genetic constraint (gnomAD): Missense variants: 327 observed, 309.94 expected, observed/expected ratio (o/e) 1.06, 90% interval 0.96 to 1.16. Synonymous variants: 123 observed, 114.65 expected, observed/expected ratio (o/e) 1.07, 90% interval 0.93 to 1.25.
Homologues: Orthologues: chimpanzee TAS2R50 (98% identical), macaque TAS2R50 (89% identical), dog CAFA-T2R43 (60% identical), mouse Tas2r120 (49% identical), rat Tas2r120 (47% identical), mouse Tas2r136 (44% identical), rat Tas2r136 (44% identical). Paralogues in human: TAS2R46 (70% identical), TAS2R31 (69% identical), TAS2R30 (69% identical), TAS2R43 (68% identical), TAS2R19 (65% identical), TAS2R20 (64% identical), TAS2R14 (44% identical), TAS2R13 (43% identical), TAS2R7 (36% identical), TAS2R9 (35% identical), TAS2R42 (35% identical), TAS2R8 (35% identical), and 11 more.
Diseases named in the same sentence as TAS2R50 in open-access papers:
TAS2R50 is named in the same sentence as 7 diseases in open-access papers, as found by Europe PMC text mining. Sharing a sentence is not in itself a finding about the gene and the disease. The quoted sentences say what the papers report.
colorectal adenoma (2 papers, 2020 to 2021). An adenoma that arises from the colon or rectum. "In a cohort study of colorectal adenoma cases, researchers explored the association between colorectal adenoma risk, dietary intake and genetic variation in three TAS2R genes: TAS2R38 (rs713598, rs1726866, rs10246939), TAS2R16 (rs846672) and TAS2R50 (rs1376251)." (PMID 32708215, 2020). "In contrast, in a multi-ethnic case–control study, neither the risk for developing colorectal adenoma nor most selected dietary variables were associated with several genetic variations of the bitter taste receptor genes TAS2R16, TAS2R38 and TAS2R50." (PMID 34885005, 2021).
myocardial infarction (1 paper, 2010). Gross necrosis of the myocardium, as a result of interruption of the blood supply to the area, as in coronary thrombosis. "As with the TAS2R50 bitter receptor gene, a single nucleotide polymorphism in the OR13G1 (olfactory receptor, family 13, subfamily G, member 1) gene has been linked with an increased risk of myocardial infarction." (PMID 20352025, 2010).
ovarian carcinoma (1 paper, 2023). A malignant neoplasm originating from the surface ovarian epithelium. "Our study revealed that high expression of TAS2R10, TAS2R3, and TAS2R50 is significantly associated with poor prognosis in ovarian cancer, as demonstrated by our analysis of clinical samples." (PMID 37799274, 2023).
tumor (2 papers, 2021 to 2023). "A significant increase in TAS2R10, TAS2R3, and TAS2R50 expression was observed in PNI-positive tumor tissue samples compared to PNI-negative." (PMID 37799274, 2023).
TAS2R50 also shares sentences with these, for which no sentence is quoted: cancer (1 paper); cardiovascular disease (1); respiratory infection (1).